S100B (S100 calcium binding protein B)
Diseases named in the same sentence as S100B in open-access papers (continued):
Sharing a sentence is not in itself a finding about the gene and the disease.
injury (continued). "In addition, considering its relatively short half-life ranging from 20 to 120 min, S100B can be used as a biomarker for traumatic brain injury when measured within a timeframe that aligns with its clearance kinetics." (PMID 39177800, 2024). "Interestingly, it should also be noted, on the other hand, that increased dentate neurogenesis, as well as hippocampal synaptogenesis, have been reported after intraventricular administration of S100B in an experimental model of traumatic brain injury." (PMID 37298554, 2023). "Moreover, S-100B at a cut-off of 8.5 ng/mL reached the specificity and sensitivity of 90% and 71%, respectively, as a predictor of brain injury in term newborns." (PMID 36597568, 2022). "Moreover, intracerebroventricular injection of S100B has also been reported to induce dentate neurogenesis and improve cognitive function in the model of experimental traumatic brain injury (lateral fluid shock)." (PMID 35615727, 2022). "S100B protein has been considered a sensitive marker of cerebral trauma." (PMID 35627746, 2022). "However, the use of S-100B in the detection of brain damage is controversial and several factors affect the accuracy of S-100B as a biomarker for brain injury." (PMID 34692564, 2021). "The half-life of S100B is relatively short (about 30 minutes), so the continuous rising of S100B may be a sign of persistent brain injury." (PMID 34160445, 2021). "Coupled with the half-life of S100B being in the range of 60 to 120 minutes in patients with brain injury, the measured net amount of S100B in serum samples will inevitably be less than the original concentration due to the rate of degradation when using ELISA methodology." (PMID 31067852, 2019). "The elevated S100β levels are observed in cerebrospinal fluid (CSF) and peripheral blood under many pathological conditions, such as ischemic stroke and traumatic brain injury." (PMID 28630527, 2017). "Thus, there is a clinical interest in studying the kinetics of S100B following traumatic brain injury." (PMID 27957604, 2017). "S100B levels in blood at 24 h post-traumatic brain injury provides an early and sensitive biomarker for the prediction of brain damage which may be useful in defining early risk patterns." (PMID 27468268, 2016). "In recent years S100-B has been reported to have a very high specificity for death (95% to 98%) and unfavourable neurological outcomes (85 to 98%), and a very high sensitivity for the diagnosis of brain lesions (99 to 100%) in traumatic brain injury." (PMID 25849778, 2015). "Many studies have therefore suggested that elevated serum S100B could be a useful surrogate marker of blood-brain leakage; indeed, this proposal is supported in clinical and animal head trauma findings." (PMID 24137128, 2013). "In conclusion, our findings suggest that cesarean delivery under either anesthetic technique does not significantly alter maternal S100β levels, and thus may not be associated with acute brain injury." (PMID 40870426, 2025). "Previously, we found the acute therapeutic application of S100B at nanomolar concentrations to promote hippocampal progenitor cell proliferation, differentiation, and migration, and to improve the functional hippocampal-dependent outcome after experimental brain injury in rats." (PMID 36076994, 2022). "Therefore, S100β may be used as a common reporter for brain damage after ischemic or traumatic brain injury onset." (PMID 28630527, 2017). "Furthermore, S100B below a threshold level may also safely eliminate the need to obtain a CT scan in patients with mild traumatic brain injury." (PMID 27468268, 2016). "In patients with craniocerebral trauma, serum levels of MMP-9, S100-β,and GFAP were found to be significantly altered." (PMID 39801405, 2025).
injury (continued). "Cerebral blood flow or perfusion pressure were not measured to investigate the direct impact of hypotension on brain dysfunction although increased serum S100B values can reflect BBB leakage and/or evolving brain injury in critically ill patients." (PMID 30086136, 2018). "The comparison of S100B between the control group and patients after head trauma (TrAlc + NonTrAlc) revealed that the serum marker level was higher in the latter group (0.092 vs. 0.99 μg/L), and the difference was statistically significant (p < 0.001)." (PMID 38138951, 2023). "Observed changes in GFAP and NSE concentration supported the assumption that S100B is released from muscles acting as a myokine rather than from the central nervous system indicating traumatic brain injury." (PMID 37063956, 2023). "While serum S100B levels fail to reflect the progressive injury in TBM, serial measurement of S100B has been proposed to have prognostic value in pediatric patients after traumatic brain injury." (PMID 35250814, 2022). "The aim of this study was to investigate the diagnostic accuracy of early prehospital S100B and GFAP measurements to rule out intracranial lesions in adult patients with mild traumatic brain injury." (PMID 34078435, 2021). "That was to say, maybe specific assortments of molecules among S100B protein, NSE, miR‐210, and miR‐374a could achieve a higher accuracy for particularized brain injury." (PMID 29568675, 2018). "In particular, early biomarkers of structural damage, such as S-100B, GFAP, and UCH-L1 may be used to assist physicians in assessing a brain injury and determining whether to order a head CT scan for patient with a mild TBI." (PMID 26016501, 2015). "The underlying mechanism describing the passage of S100B from brain to blood following acute brain injury has not yet been clarified, nor does an unequivocal data interpretation exist regarding cerebral S100B levels and their correlation to serum S100B levels." (PMID 20671945, 2010). "For example, treatment with synaptamide in traumatic brain injury or sciatic nerve chronic constriction injury decreased astrogliosis and immunoreactivity and reduced the levels of inflammatory biomarkers such as glial fibrillary acidic protein (GFAP), S100β, and IL-6." (PMID 38338779, 2024). "Regarding S100B protein, it was usually detected within blood, CBF, saliva, amniotic fluid, and breast milk, and its increase could precisely predict severity and prognosis of brain injury." (PMID 29568675, 2018). "Furthermore, S100B can be expressed in case of traumatic or nontraumatic brain injury." (PMID 30581620, 2018). "Increased levels of S100B in blood is however not specific for ICH, as increases occur in other neuropathologies including traumatic brain injury and extracranial malignancies and has been shown to represent ongoing neurogeneration." (PMID 24696689, 2014).
ischemic stroke (68 papers, 2010 to 2025). A stroke disorder caused by obstruction of blood flow to the brain, due to thrombotic (local blood clot formation) or embolic (due to a blood clot or other material traveling from another site) event. "The findings demonstrate the importance of S100B as a prognostic and diagnostic biomarker in ischemic stroke, suggesting underlying neuroinflammatory processes and BBB disruption." (PMID 40949500, 2025). "This is intriguing because S100B is an indicator of the size of the infarct core, and so we had expected to find at least a correlation between S100B levels and ischemic stroke caused by large artery atherosclerosis (LAA)." (PMID 38248781, 2024). "In contrast, in an ischemic stroke, S100B was proven to be of limited value as a diagnostic marker, even though it showed some prognostic power." (PMID 32575870, 2020). "For example, the concentration of S100B increases in the plasma of patients with ischemic stroke, and levels are associated with a larger infarct size, poor neurovascular status on admission, and worse outcomes." (PMID 30034558, 2018). "Following an ischaemic stroke, S100B has been reported to be released into the bloodstream as a result of glial cell activation and breakdown of the blood–brain barrier (BBB)." (PMID 41150802, 2025). "A transient increase in serum S100B levels was also observed in apnoeic divers, and this increase was comparable to that seen in patients after ischaemic stroke." (PMID 40243713, 2025). "S100B, a calcium-binding protein of astrocyte origin, has been investigated as an ischemic stroke biomarker." (PMID 40949500, 2025). "For example, s100b is an astroglial protein that has traditionally been studied in patients with different types of brain injuries, including ischemic stroke, and is related to the degree of injury and the functional outcome." (PMID 41149263, 2025). "We first found that Slc4a4 was highly expressed in S100b+ reactive astrocytes, suggesting its potential role after ischemic stroke." (PMID 38709635, 2024). "Ultimately, we suggest that serum S100B protein levels can predict the course of ischemic stroke in the context of short- and long-term functional outcomes." (PMID 38248781, 2024). "We investigated serum S100B levels, to determine the initial stages of mild cognitive impairment and the development of ischemic stroke." (PMID 39452859, 2024). "The results of clinical studies conducted in recent years have suggested that patients with ischemic stroke have significantly elevated blood levels of S100B." (PMID 38248781, 2024). "The aim of our study was to investigate the relationship between serum S100B levels and their changes over time and short- and long-term functional outcomes in patients with ischemic stroke." (PMID 38248781, 2024). "This study aims to evaluate the correlation between miRNAs and known nerve injury markers neuron-specific enolase (NSE) and S100β in ischemic stroke (IS) patients, exploring its efficacy." (PMID 39669376, 2024). "Given the short half-life of this protein and renal clearance, serum S100B levels illustrate the course of ischemic stroke in real-time." (PMID 38248781, 2024). "Similar to traumatic brain injury and subarachnoid hemorrhage, functional recovery of patients with ischemic stroke can be predicted by measuring serum S100B." (PMID 37474905, 2023). "S100B levels in peripheral tissues after ischemic stroke have been significantly elevated in patients and animals." (PMID 37342100, 2023). "Previous studies have shown the astrocytic marker S100B to be a valid marker of ischemic stroke and traumatic brain injury in the emergency setting." (PMID 36747206, 2023). "S100B levels are increased in haemorrhagic stroke compared to ischemic stroke in several studies, thus allowing a distinction between the two forms of brain damage." (PMID 37511304, 2023).
ischemic stroke (continued). "In routine cardiac surgery, postoperative elevated levels of S100B have been shown to correlate with ischemic stroke and other neurocognitive disorders, and S100B levels have been shown to correlate with the extent of neurological damage." (PMID 36747206, 2023). "S100B can be released into the bloodstream following ischemic stroke due to glial cell activation and blood–brain barrier disruption." (PMID 37752283, 2023). "S100B is widely used in neurological disorders as a biomarker of blood–brain barrier leakage in mild traumatic brain injury, ischemic stroke, and spontaneous subarachnoid hemorrhage." (PMID 37759935, 2023). "In another study, S100B was measured in blood 3 months after ischemic stroke and a significant correlation between high levels of S100B and worse prognosis (measured by the mRS and NIHSS) was observed." (PMID 36699006, 2022). "Several previous studies showed that serum biomarkers such as S100B, NfL, CAF, and Glial fibrillary acidic protein (GFAP) were associated with the prognosis of ischemic stroke, ICH and traumatic brain injury." (PMID 36068493, 2022). "A previous study showed that both S100B and GFAp in CSF increased similarly in a time and volume dependent manner after ischaemic stroke." (PMID 33723754, 2022). "S100b has been investigated as a possible biomarker to distinguish hemorrhagic stroke from ischemic stroke and some studies have shown that S100b concentrations in blood were higher for hemorrhagic stroke compared to ischemic stroke." (PMID 36756347, 2022). "S100B was elevated in ischemic stroke compared to control and correlated with neurological deficits, infarction, and edema, but not with the functional prognosis." (PMID 33115334, 2021). "S100β, a calcium dependent protein which is produced primarily by astrocytes in the CNS, is released into the serum and CSF 24–96 h after ischaemic stroke onset." (PMID 33924191, 2021). "This process of reactive gliosis is characterized by a pronounced increase in GFAP and S100B, supporting their potential role as prognostic markers in ischemic stroke." (PMID 32595585, 2020). "The functional outcomes were evaluated 6 months after ischemic stroke by the Barthel index, which was correlated with the age and levels of sTREM-1 and S100B." (PMID 33375339, 2020). "Using the very sensitive single-molecule array (simoa) technique, we determined plasma NF-L concentrations in ischemic stroke and TIA patients, and healthy controls and their association with disability scores, functional outcome, S100B, and IL-6 levels." (PMID 32595585, 2020). "Clinically, elevated levels of NSE and S100B protein have been observed early following ischemic stroke, and elevated levels of S100B protein have been observed after intracerebral and subarachnoid hemorrhage." (PMID 32024492, 2020). "TCONS_00090385 would compete with miR-129-2-3p and regulated the expression of S100b in ischemic stroke." (PMID 29516010, 2018). "It is well known that both the high baseline NIHSS score and the high serum S100β levels predict poor prognosis of ischemic stroke, which was also found in the present study." (PMID 22206485, 2011). "Such future studies will go on to address the tantalizing possibility of next-generation therapeutics for ischemic stroke and AD aimed at the pleiotropic S100B pathway." (PMID 20862385, 2010). "In a previous study body fluid biomarkers for brain damage after ischemic stroke including S100B, glial fibrillary acid protein (GFAP) and ubiquitin C-terminal hydrolase (UCH-L1) were significantly lower in the EPO treated patients than in placebo treated ones." (PMID 40791908, 2025). "There is evidence that RIC either reduces or attenuates the rise of S100β in ischaemic stroke." (PMID 39702489, 2024). "Some studies have also revealed that S100B levels correlate with the severity of ischemic stroke, as measured by the NIHSS, and may be useful in determining functional prognosis." (PMID 38248781, 2024).
ischemic stroke (continued). "S100β usually rises following ischaemic stroke; this may be proportionate to the magnitude of infarction and associated with blood–brain barrier permeability." (PMID 39702489, 2024). "In addition, S100-β has been reported to be used as a biomarker for the diagnosis of cerebral ischemia and ischemic stroke." (PMID 39669377, 2024). "In ischemic stroke, S100B is released into the blood and cerebrospinal fluid." (PMID 38248781, 2024). "Serum S100B has been extensively investigated in ischemic stroke patients." (PMID 37474905, 2023). "This mini review covers available applications of the S100B protein in prognosticating clinical outcome in patients with various neurological disorders, particularly in those with traumatic brain injury, spontaneous subarachnoid hemorrhage and ischemic stroke." (PMID 37474905, 2023). "Similarly, high concentrations of S100B (blood samples taken 24 h after symptom onset) detected in serum by ELISA, were associated with more severe neurological deficits (NIHSS>10) after ischemic stroke." (PMID 36699006, 2022). "Previous studies showed that several factors including neurofilament light (NfL), C-terminal Agrin Fragment (CAF), volume of hematoma, white matter hyperintensities, Alberta Stroke Program Early CT Score (ASPECTS) score, S100B protein would influence the outcome of ischemic stroke rehabilitation." (PMID 36068493, 2022). "High levels of S100B in serum could significantly predict the level of neurological disability at 3 months after ischemic stroke, measured by the BI, mRS, and Lindley score." (PMID 36699006, 2022). "In 130 patients with acute focal neurologic deficits admitted within 6 h of onset of symptoms, a panel including D-dimer, CRP, B-type natriuretic protein (BNP), MMP-9, and S100B was predictive of ischemic stroke with sensitivity and specificity of 81 and 70%, respectively." (PMID 33633673, 2021). "S100B was significantly increased in ischemic stroke vs. ICH." (PMID 33115334, 2021). "S100β is widely expressed in various glial cells of the CNS in mammals, and previous studies have shown satisfactory sensitivity and specificity for serum S100β in the diagnosis of ischemic stroke after cardiac surgery." (PMID 34859071, 2021). "S100b levels were decreased in both groups with prior TIA before ischemic stroke." (PMID 33192985, 2020). "Serum S100B values obtained in acute ischemic stroke patients 24–72 h after symptom onset, but not at earlier time points, have been shown to predict functional outcome and infarct volume in ischemic stroke patients." (PMID 32595585, 2020). "The levels of serum S100B were elevated in patients with ischemic stroke (IS), which may be a novel biomarker for diagnosing IS." (PMID 29343763, 2018). "Indeed, a comparable relationship between serum S100B and ischemic stroke has been described in the literature." (PMID 27007976, 2016). "Overall, serum S100B levels peak 2-3 days after an ischaemic stroke." (PMID 21034449, 2010). "These and other studies unequivocally suggest that inhibiting astrocytic activation by pharmacological blockade of S100B biosynthesis may be a valuable therapeutic strategy to combat ischemic stroke and to delay onset and/or progression of AD." (PMID 20862385, 2010). "Regarding acute diagnostic, S100B has a low specificity for ischemic stroke and its serum levels doe not seem to increase immediately after acute stroke and might reach the highest values at day 3 after symptom onset." (PMID 37474905, 2023). "Moreover, a large number of clinical studies have demonstrated that the S100B levels are elevated in the CSF and/or serum of patients with various neuropsychiatric diseases, including schizophrenia, bipolar disorder, ischemic stroke, multiple sclerosis and AD." (PMID 33982673, 2021). "High S100B and low soluble RAGE levels were detected in the blood of hemorrhagic stroke patients compared with those presenting with ischemic stroke." (PMID 40949500, 2025).